ZNF383 (zinc finger protein 383)
Description:
May function as a transcriptional repressor, suppressing transcriptional activities mediated by MAPK signaling pathways.
Synonyms: HSD17; FLJ35863; Zfp383
Tractability: PROTAC: ubiquitination databases record sites on it.
Gene: Protein-coding gene on chromosome 19 (37,217,926 to 37,248,740, forward strand). Ensembl gene ENSG00000188283.
Subcellular location: Nucleus; Cytoplasm
Subcellular location (Human Protein Atlas): Nuclear membrane; Nucleoplasm
Pathways (Reactome):
Gene expression (Transcription): Generic Transcription Pathway
Gene Ontology:
Molecular function: protein binding; DNA-binding transcription factor activity; RNA polymerase II cis-regulatory region sequence-specific DNA binding
Biological process: regulation of transcription by RNA polymerase II; regulation of DNA-templated transcription
Cellular component: nuclear membrane; nucleoplasm; nucleus; cytoplasm
Genetic constraint (gnomAD): Loss-of-function variants: 32 observed, 48.28 expected, observed/expected ratio (o/e) 0.66, 90% interval 0.5 to 0.89. The upper end of that interval is the gene's LOEUF score, 0.89, which puts it in group 3 of 6, group 1 being the genes least tolerant of losing a copy. Missense variants: 475 observed, 580.72 expected, observed/expected ratio (o/e) 0.82, 90% interval 0.76 to 0.88. Synonymous variants: 153 observed, 191.24 expected, observed/expected ratio (o/e) 0.8, 90% interval 0.7 to 0.92.
Homologues: Orthologues: pig ZNF383 (94% identical), rabbit ZNF383 (93% identical), mouse Zfp383 (84% identical), rat Zfp420 (84% identical). Paralogues in human: ZNF829 (68% identical), ZNF790 (58% identical), ZNF780B (56% identical), ZNF780A (56% identical), ZNF546 (54% identical), ZNF30 (54% identical), ZNF540 (51% identical), ZFP14 (50% identical), ZFP82 (50% identical), ZFP30 (50% identical), ZNF879 (49% identical), ZNF33B (49% identical), and 164 more.
Diseases named in the same sentence as ZNF383 in open-access papers:
ZNF383 is named in the same sentence as 3 diseases in open-access papers, as found by Europe PMC text mining. Sharing a sentence is not in itself a finding about the gene and the disease. The quoted sentences say what the papers report.
glioma (1 paper, 2019). A benign or malignant brain and spinal cord tumor that arises from glial cells (astrocytes, oligodendrocytes, ependymal cells). "Therefore, which gene, such as HDAC7, ERCC1, LTBP4 and ZNF383, could play a major role in glioma proliferation need further study and investigation." (PMID 30691485, 2019).
leukemia (1 paper, 2021). A malignant (clonal) hematologic disorder, involving hematopoietic stem cells and characterized by the presence of primitive or atypical myeloid or lymphoid cells in the bone marrow and the blood. "Compared to healthy BMMCs, we observed the TF networks of ZNF266, RORA, GTF3C2, ZNF76, ZNF383, IRF5 and NFE2L2 being top upregulated in all leukemia patients." (PMID 33408321, 2021).
tumor (1 paper, 2021). "For example, ZNF545, ZNF569, ZNF383, and ZNF331 are reported to act as tumor suppressor genes, while ZNF147, ZNF217, ZNF278, GLI1, and Evi9 promote tumor progression." (PMID 33566221, 2021).